OR51M1 (olfactory receptor family 51 subfamily M member 1)
Description:
Odorant receptor.
Synonyms: HOR5'Beta7; OR11-40
Tractability: Antibody: UniProt places it where antibodies can reach, with medium confidence; UniProt predicts a signal peptide or a membrane-spanning region; its Gene Ontology location is reachable by antibodies, with medium confidence.
Gene: Protein-coding gene on chromosome 11 (5,383,812 to 5,393,263, forward strand). Ensembl gene ENSG00000184698.
Subcellular location: Cell membrane
Pathways (Reactome):
Sensory Perception: Expression and translocation of olfactory receptors
Gene Ontology:
Molecular function: olfactory receptor activity; G protein-coupled receptor activity; signaling receptor activity
Biological process: sensory perception of smell; cellular response to lipid; detection of chemical stimulus involved in sensory perception of smell; G protein-coupled receptor signaling pathway; system process
Cellular component: membrane; plasma membrane
Genetic constraint (gnomAD): Loss-of-function variants: 0 observed, 0.28 expected, observed/expected ratio (o/e) 0, 90% interval 0 to 1.87. That is too few expected variants to judge how well the gene tolerates losing a copy. Missense variants: 509 observed, 419.96 expected, observed/expected ratio (o/e) 1.21, 90% interval 1.13 to 1.3. Synonymous variants: 199 observed, 161.1 expected, observed/expected ratio (o/e) 1.24, 90% interval 1.1 to 1.39.
Homologues: Orthologues: chimpanzee OR51M1 (96% identical), macaque OR51M1 (94% identical), rabbit OR51M1 (86% identical), dog OR51M1 (83% identical), mouse Or51m1 (81% identical), pig OR51M1 (77% identical). Paralogues in human: OR51G1 (51% identical), OR51G2 (50% identical), OR51I2 (49% identical), OR51C1 (47% identical), OR51L1 (47% identical), OR51F2 (46% identical), OR51Q1 (46% identical), OR51I1 (45% identical), OR51V1 (45% identical), OR51A4 (44% identical), OR51A7 (44% identical), OR52K2 (44% identical), and 39 more.
Diseases named in the same sentence as OR51M1 in open-access papers:
OR51M1 is named in the same sentence as 2 diseases in open-access papers, as found by Europe PMC text mining. Sharing a sentence is not in itself a finding about the gene and the disease.
OR51M1 shares sentences with these, for which no sentence is quoted: genetic diseases (1 paper); melanoma (1).